IGF1R (insulin like growth factor 1 receptor)
Diseases named in the same sentence as IGF1R in open-access papers (continued):
Sharing a sentence is not in itself a finding about the gene and the disease.
breast cancer (continued). "For example, IGF1R is overexpressed in HER2+ breast cancer, and forms a heteromeric complex with HER2 and HER3 to activate the PI3K signaling pathway, conferring trastuzumab resistance to breast cancer patients." (PMID 33083021, 2020). "Our analysis revealed that a high expression of IGF-1 or IGF-1R (or both) does not affect the OS or DFS rates in patients with ER/PR-positive and HER2-negative breast cancer subtype, but it associates with a reduced DFS rate in TNBC patients." (PMID 32325700, 2020). "While HER3 signaling also induces lapatinib resistance in the trastuzumab-resistant breast cancer cells, IGF-1R signaling did not alter lapatinib sensitivity." (PMID 30930695, 2019). "In addition, there was a correlation between IGF-1R signaling pathway and MUC1 expression in breast cancer cells." (PMID 30041514, 2019). "FUT8 promotes breast cancer cell invasiveness by remodeling TGF-β receptor core fucosylation and drives the proliferation and invasion of trophoblastic cells via the Insulin-like growth factor 1 (IGF-1)/IGF-1R signaling pathway." (PMID 31022917, 2019). "The role of AR in KIRC progression is not clear, but it has been shown that in prostate and breast cancer cells AR binds to IGF1R promoter and thus increases IGF1R expression." (PMID 31888623, 2019). "Among the candidate target genes, PTEN was the potential target for miR-940, IGF1R for miR-451a and miR-16-5p, and SRC for miR-17-3p, as aberrant signaling of PTEN, IGF1R, and SRC has been involved in trastuzumab resistance of breast cancer cells." (PMID 29691399, 2018). "Notably, conditioned media from IGF-1Ea-transfected HEK293 cells treated with Tun was unable to activate the IGF-1 receptor (IGF-1R) and downstream phosphorylation of ERK1/2 and AKT of MCF-7 breast cancer cells." (PMID 29891966, 2018). "Of a total of 113 CTCs detected in metastatic patients, 18% lacked IGF1R and E‐cadherin expression (P = 0.014, compared to early breast cancer)." (PMID 28766847, 2018). "Moreover, CHOP and MMP2 expression were upregulated in tumors with low IGF-1R, whereas expression was unchanged in TNBC compared to ER+/PR+ breast cancer revealing CHOP and MMP2 are more correlated with IGF-1R levels than with hormone receptor status." (PMID 30458886, 2018). "Interestingly, MMP2 and CHOP were also upregulated in human tumors with low IGF-1R, similar to our mouse model, whereas these two genes were unchanged in TNBC compared to ER+/PR+ breast cancer." (PMID 30458886, 2018). "Moreover, IGF1R has been reported to be essential for sustaining mesenchymal morphologies and plays an important role in regulating EMT in breast cancer." (PMID 29507664, 2018). "Importantly, analysis from the METABRIC dataset of patient overall survival in both ER+/PR+ breast cancer and TNBC revealed low expression of IGF-1R significantly correlates with worse overall survival compared to high expression of IGF-1R." (PMID 30458886, 2018). "IGF-1R expression was inversely correlated with patient survival even within hormone receptor-positive breast cancers, indicating reduced overall patient survival with low IGF-1R was not due simply to low IGF-1R expression within TNBCs." (PMID 30458886, 2018). "MCF7, a luminal human breast cancer cell line, has high levels of IGF-1R whereas HCC70, a basal-like breast cancer cell line, has intermediate levels of IGF-1R, and MDA-MB-231, a mesenchymal-like TNBC line, has low levels of IGF-1R relative to each other." (PMID 30458886, 2018). "Therefore, novel therapeutic approaches to overcome primary and secondary resistance to trastuzumab include inhibition of angiogenesis and other signaling pathways (PI3K/mTOR, IGF1-R, HSP90) involved in breast cancer growth." (PMID 28533703, 2017). "In turn, a specific siRNA for IGF-1R prevents adiponectin-induced ERα transactivation, thus proving the existence of a functional interplay among adiponectin/AdipoR1, ERα, and IGF-1R, promoting ERα+ breast cancer cell growth." (PMID 29036907, 2017).
breast cancer (continued). "In addition, miR-152 plays an important role in breast cancer cell proliferation and angiogenesis via PKM2/NF-κB/EGR1/miR-152 complex in respond to IGF-1R activation." (PMID 29162853, 2017). "Furthermore, IGF1/IGF1R signaling, which has angiogenic effects, has been shown to activate GPER in breast cancer cells." (PMID 29212519, 2017). "To test whether the regulation of miR-29a in breast cancer cells cultured in human insulin medium was directly related to the IGF-1R, CDC42, or p85α, we knocked down the IGF-1R, CDC42, and p85α using siRNA." (PMID 28427228, 2017). "Growth factor receptors, such as epidermal growth factor receptor 1 (EGFR), human epidermal growth factor receptor 2 (HER2), and insulin-like growth factor 1 receptor (IGF1R), are key regulatory nodes of the GFRN and are often aberrantly activated across breast cancer subtypes." (PMID 28446242, 2017). "Moreover, modulation of IGF1R was reported to regulate EMT, particularly in breast cancer, and self-renewal of CSCs." (PMID 28947975, 2017). "In addition, a correlation between IGF‐1R and downstream PI3K pathway activation was reported in drug resistance, and IGF‐1R and PI3K dual treatments act synergistically in targeting breast cancer cells." (PMID 28296140, 2017). "Cell viability and colony formation in vitro studies were completed using estrogen receptor (ER) positive and negative breast cancer cell-lines to determine the benefit of IGF1R inhibitor (OSI-906) and SphK inhibitor (SKI-II) co-therapy." (PMID 29207959, 2017). "Our previous data indicate that, in breast cancer cells, DDR1 interacts with IGF-1R and positively modulates IGF-1R expression and biological responses, suggesting that the DDR1-IGF-IR cross-talk may play an important role in cancer." (PMID 26655502, 2016). "Though not a common therapy for all breast cancers, cisplatin is being investigated for use in triple negative breast cancers, in which IGF-1R has been shown to have high activity." (PMID 27472395, 2016). "Interestingly, ten highly ranked statistically significant putative regSNVs (p < 1.0E-03) appeared close to genes previously shown to be oncogenic in breast cancer such as PVT1, IGF1R, and GREB1." (PMID 27964748, 2016). "Trastuzumab-induced resistance through various receptor tyrosine kinases including IGF1R and HER3 has been described in ovarian and breast cancer, and the latter study also described antitumor activity of a combination of trastuzumab and a HER3 inhibitor on trastuzumab-resistant cells." (PMID 26863569, 2016). "In contrast to a small molecule inhibitor targeting IGF-1R and insulin receptor (IR), MK-0646 failed to improve anti-tumor response to hormonal therapy in ER-positive breast cancer xenografts." (PMID 27765027, 2016). "While levels of total and IGF-1R have been identified as poor prognostic factors in breast cancer, levels of IGF-1R expression have not been shown to predict benefit from anti-IGF therapeutics." (PMID 26991655, 2016). "Here, we confirmed these results, as mammary tumors initiated by IGF1R-KD cells developed only slightly, but not significantly, slower compared to the control tumors in female FVB/N mice." (PMID 27179633, 2016). "The T47D-YA breast cancer variant cell line does not express IRS adaptor proteins or respond to IGF ligands, yet they retain functional IGF-1R." (PMID 26991655, 2016). "Although in PTEN null breast cancers, p110β activity was induced by G protein coupled receptor (GPCR), in our models of resistance to BYL719, p110β is activated in an IGF1R/IRS-dependent manner and contributes to AKT and mTOR activation, and ultimately to resistance to p110α inhibition." (PMID 27048245, 2016). "Unfortunately, a general lack of activity is a common stigmata of IGF-1R inhibitors in breast cancer." (PMID 27765027, 2016).
breast cancer (continued). "The rationale behind our hypothesis was that in breast cancer cell lines resistant to tamoxifen, a cross-talk mechanism has previously been identified between EGFR and the IGF1R signaling pathway." (PMID 25599599, 2015). "In vitro work in MCF7 breast cancer cells demonstrated that BRCA1 knockdown induces the expression of IGF-1 mRNA in an estrogen receptor α-dependent manner, which was shown to correspond with increased IGF-1R activation and signaling." (PMID 26217584, 2015). "For all-cause and breast cancer-specific mortality, no heterogeneity of effects was observed by race/ethnicity for IGF1 (P for interaction 0.26 and 0.45, respectively), IGF1R (P for interaction 0.43 and 0.72), or IGFBP2 (P for interaction 0.49 and 0.32)." (PMID 25619494, 2015). "This is particularly true for the TN breast cancer cells (estrogen-unresponsive), in which IGF1R is largely expressed and IGF-1 stimulates proliferation and survival, making them responsive in vitro to anti-IGF1R therapies." (PMID 26449867, 2015). "Furthermore, studies with breast cancer cell lines have shown that MEK inhibition also increases sensitivity to EGFR blockade, and reversed the effects of IGF-1R overexpression in promoting proliferation." (PMID 25975820, 2015). "Our data further suggests that IGF-1R inhibition suppresses HR by downregulation of RAD51, and that this allows a strong antitumor activity in combination with PARP inhibitors in BRCA1 wild-type (HR proficient) ovarian and breast cancer cells." (PMID 26510816, 2015). "Unlike clinical data, in vitro breast cancer cell line data suggest a strong correlation between increased IGF1R activity and trastuzumab-resistance." (PMID 25964777, 2015). "IGF1R signaling may also independently impact ERβ expression, as silencing of this receptor in MCF-7 breast cancer cells has been shown to increase ERβ levels." (PMID 26709918, 2015). "LL-2003 exhibited similar effects on cell viability, the phosphorylation of IGF-1R and Src, and induction of PARP cleavage in MCF7 human breast cancer cells, suggesting LL-2003 could be applicable to other types of cancers." (PMID 26515601, 2015). "Furthermore, a high mRNA ratio of IGFBP-5/IGFBP-4 from patients’ tissue enhanced the power of its poor prognostic value, and also predicted resistance to the IGF-1R and INSR TKI, BMS-536924, in a breast cancer cell line." (PMID 26217584, 2015). "One study used two murine mammary tumour cell lines, both expressing INSR and IGF1R." (PMID 26242987, 2015). "However, the relationship between the IGF1R component of IGF and tumor growth in breast cancer requires more elucidation." (PMID 24392142, 2014). "IGF1R has been shown to be present in all breast cancer subtypes, regardless of the hormone receptor or HER2 status, with overall IHC expression rates ranging from 43.8% to 87%." (PMID 24637962, 2014). "Importantly, we have shown that the expression of IGF1R mRNA is up-regulated in WBC from the carriers and down-regulated in WBC from the breast cancer patients (p = 0.025)." (PMID 25403427, 2014). "Taken altogether, these results suggest that aberrant expression of components of the IGF1R-mediated pathway is associated with better clinical outcomes in women with hormone receptor positive, HER2 negative, node positive early breast cancer." (PMID 24637962, 2014). "For molecular imaging strategies, a putative panel consisting of markers for EGFR, IGF1-R, FGFR2, GLUT1, CAXII, CD44v6 was positive in 77% of cases and might be considered for development of molecular tracers for male breast cancer." (PMID 23308200, 2013). "In view of the reported involvement of IGF-1R signaling in the metastasis and epithelial-mesenchymal transition (EMT) of breast cancer cells, we further investigated whether IGF-1R signal also regulates EMT process in CD44+ BCSCs." (PMID 23663564, 2013).
breast cancer (continued). "According to the authors, the greatest advantage of targeting the IGF system is its crosstalk with other signalling pathways, as preclinical work has identified significant antitumor activity when IGF-1R is concordantly targeted with mTOR, ERα, the EGF receptor and HER2 in breast cancer." (PMID 23483937, 2013). "IGF-1R expression in BCSCs and noncancer stem cells sorted from xenografts of human primary breast cancers was examined by fluorescence-activated cell sorting (FACS), western blot analysis and immunoprecipitation." (PMID 23663564, 2013). "Expression of phosphorylated IGF-1R was greater in BCSCs than in non-BCSCs from xenografts of human breast cancer, which were supported by western blot and immunoprecipitation experiments." (PMID 23663564, 2013). "This form of receptor transactivation has been shown to regulate cell proliferation, migration and invasion in various types of cancer, and our recent data indicate an important role for IGF-1R and CXCR4 transactivation in migration of MDA-MB-231 breast cancer cells." (PMID 23320409, 2013). "Also, while most research addressing the need to complement targeted therapies of breast cancer concentrates on the HER family, an alternative approach directed at the IGF1R-dependent signaling deserves attention." (PMID 22799881, 2012). "Western blotting studies showed that MSM can effectively down-regulate the expression of STAT5b as well as IGF-1R in both aggressive and non-aggressive human breast cancer cell lines." (PMID 22485142, 2012). "In addition, HSE treatment inhibited STAT5b/IGF-1R and STAT3/VEGF-dependent luciferase activities in breast cancer cells." (PMID 22792362, 2012). "We showed that 80% of all breast cancers express at least one of a panel of markers (CD44v6, GLUT1, EGFR, HER2, and IGF1-R) that therefore may be suitable for molecular imaging strategies." (PMID 22695343, 2012). "After being respectively treated with UTI, TXT and UTI+TXT for 48h, the gene expression of IGF-1R, PDGFA, NGF, NF-κB, and JNK2 in human breast cancer cells decreased significantly compared with the control group (P < 0.05) in the order of UTI+TXT > TXT > UTI > control." (PMID 22217202, 2012). "We hypothesized that HSE could suppress phosphorylation of STAT5 and STAT3, and the expression or release of IGF-1R, VEGF, VEGF-R2 and HIF-1α proteins in human breast cancer xenografts in vivo." (PMID 22792362, 2012). "IGF1R and AR inhibitors are currently tested separately in the clinic in this context, whereas ERBB3 has not previously been linked to the biology of ER+ breast cancer." (PMID 22343619, 2012). "In ER-positive breast cancer cells, IGF-1R and ERα are often coexpressed and respond to the synergistic action of estrogen and IGF-1 signaling, leading to cross-talk between the ER and IGF-1R pathways." (PMID 21595894, 2011). "While the accumulating data just described show that IGF-1R operates through signaling cross-talk with estrogen-ER signaling and EGFR/HER2 regulatory pathways in antiestrogen-resistant breast cancer cells, the ER-independent role of IGF-1R signaling in antiestrogen resistance is poorly understood." (PMID 21595894, 2011). "Clinical studies have revealed that phosphorylation of IGF-1R is correlated with poor outcomes of breast cancers, whereas total IGF-1R level is not." (PMID 21595894, 2011). "Recent evidence from trastuzumab-resistant breast cancer cell lines suggests that functional heterodimerization of HER2 and IGF1R may contribute to trastuzumab resistance." (PMID 22172159, 2011). "As breast cancer metastasises to distant organs, it is often not clinically feasible to biopsy these tissues and measure levels of IGF1R in those sites." (PMID 19491901, 2009). "Through its anti-IGF-1R activity, AG1024 inhibits cell proliferation and induces apoptosis in several cell systems, including non-small-cell lung cancer, small-cell lung cancer, melanoma, and breast cancer." (PMID 15987464, 2005).
breast cancer (continued). "In order to improve the antineoplastic activity of gefitinib, we investigated the effects of blocking the signalling of the insulin-like growth factor 1 receptor (IGF-1R), a tyrosine kinase with a crucial role in malignancy that is coexpressed with EGFR in most human primary breast carcinomas." (PMID 15987464, 2005). "Furthermore, the IGF‐1 receptor (IGF‐1R) can activate the Ras/Raf/MEK/ERK signaling pathway, enhancing the expression of cyclin D1 and accelerating the G1/S phase transition, thus promoting the proliferative capacity of breast cancer cells." (PMID 40550558, 2025). "Also, human samples from breast cancer tissue exhibited reduced miR-122 and increased IGF-1R expression when compared to samples from normal tissue, suggesting that miR-122 acts directly on IGF-1R." (PMID 41153350, 2025). "Therefore, 11 insulin-responsive cell lines were screened for insulin-induced EphA2 regulation, including four hepatoma (HepG2 WT, HepG2 IGF1R KO, Hep3B, and H4IIE), three acute myeloid leukemia (AML) (MOLM-13, THP1, and EOL-1), and four breast cancer cell lines (BT549, BT474, HCC38, and HCC1937)." (PMID 39572596, 2024). "This led us to hypothesize a regulatory role for C/EBP-β, a predominant oncogenic transcription factor in breast cancer, modulated by several receptor tyrosine kinases, such as EGFR, fibroblast growth factor receptor (FGFR), insulin receptor (IR), and IGF-1 receptor (IGF-1R)." (PMID 38560690, 2024). "Using the BreastMark platform and the ssp2006 classifier, we examined the differences in mRNA expression of IGF1R and IR in 2185 breast cancers, including 255 basal-like breast cancers, and found that neither expression of IGF1R nor IR was elevated in a specific subtype." (PMID 36920947, 2023). "In addition, BRCA has also been described as a metabolic regulator through its complex interactions with insulin/IGF-1 signaling axis and as transcriptional repressor of the gene IGF1R, main key players in the pathogenesis of T2DM-related complications and in breast cancer onset and progression." (PMID 37510134, 2023). "Notably, ceRNAs of miR-1294 have not been found in Breast cancer (BC), ccRCC, OC, and low expression of miR-1294 can relax the repression of HOXA6, IGF1R, thereby promoting cancer risk." (PMID 37303740, 2023). "Processes downstream of IRS-2, but independent of PI3K, that promote breast cancer invasion have not yet been extensively investigated, and future studies examining these mechanisms may reveal novel approaches for targeting IGF-1R signaling in breast cancer." (PMID 36556357, 2022). "In addition, molecular docking and simulation also identified IGF1R, MDM2, and SRC could be the prime diosgenin-modulated targets against breast cancer." (PMID 36686654, 2022). "Interestingly, IGF-1R binds to and stimulates its own promoter in the absence of ER expression in breast carcinoma cells, suggesting a unique role for the IGF-1R in ER− breast tumors, although this has not yet been elucidated." (PMID 36556357, 2022). "While interventions aimed at inhibiting the IGF-1R have not improved outcomes in breast cancer subjects to date, various elements of study design may be contributory to this outcome and further studies are ongoing." (PMID 33910628, 2021). "In addition, proliferation of breast cancer is enhanced by insulin-like growth factor 1 (IGF-1) and epidermal growth factor (EGF), which stimulate signaling through the MAPK and PI3K/AKT pathways by activation of IGF-1R and EGFR receptors, respectively." (PMID 34462889, 2021). "However, these clinical trials showed poor outcomes, resulting in no approved IGF-1R-targeting drugs in human breast cancer so far." (PMID 33664868, 2021). "A previous study demonstrated that mTOR kinase inhibition of breast cancer cells for 24 h led to inhibition of pAkt S473 but activation of pAkt T308, along with downstream effectors of Akt, because of activation of several RTKs, including ERBB family members as well as IGF1R and IR." (PMID 33273014, 2021).